CCL20 (C-C motif chemokine ligand 20)
Diseases named in the same sentence as CCL20 in open-access papers (continued):
Sharing a sentence is not in itself a finding about the gene and the disease.
rheumatoid arthritis (continued). "CCR6 is involved in mucosal humoral immunity and intestinal T cell homing, and it has recently been reported that Th17 cells expressing CCR6 are preferentially recruited to inflamed joints via its ligand CCL20 in an animal model of rheumatoid arthritis." (PMID 18698345, 2008). "Notably, the potential role of CCL20 as a biomarker has already been suggested in other autoimmune diseases, including rheumatoid arthritis and vitiligo." (PMID 41601633, 2026). "Serum levels of the inflammatory factors CXCL8 and CCL20 are elevated in rheumatoid arthritis, but whether these factors affect bone metabolism is unknown." (PMID 26103626, 2015). "CCL20 has been suggested to play a role in the pathogenesis of rheumatoid arthritis." (PMID 26103626, 2015). "Moreover CCL20 has been suggested as an emerging player in the pathogenesis of rheumatoid arthritis." (PMID 26103626, 2015). "Similarly, CCL20, a significant chemotactic factor, is elevated in rheumatoid arthritis and may have a similar role in ME/CFS." (PMID 40427027, 2025). "However, in the current study, the mechanism leading to the different driven Th17 cells count in alveolar space might differ from that in rheumatoid arthritis for the similar concentrations of CCL20 in BALF from both IL-9−/− and WT PCP mice." (PMID 29887863, 2018). "However, CXCL8 and CCL20 enhanced osteoblast-mediated osteoclastogenesis, partly via IL-6 production, suggesting that CXCL8 and CCL20 may contribute to osteoporosis in rheumatoid arthritis by affecting bone cell communication." (PMID 26103626, 2015). "In rheumatoid arthritis, CYR61 was found to be overexpressed in the synovial tissue of patients and was able to induce the expression of IL-6, CCL20, IL-1β, and MMP-3 in cultured fibroblast-like synoviocytes from patients." (PMID 33542676, 2021). "Interestingly, the five cytokines (CCL2, CCL3, CCL20, CXCL1, and IL8) that are involved in the leukocyte infiltration in the blood vessel of rheumatoid arthritis patients are also found in the xenoAMP(S)-poly(I:C) activated HDMVEC." (PMID 38306481, 2024). "Early studies on the specific blocking of either CCR6 or CCL20 included the transfer of CD4+ T cells from Sakaguchi mice into severe combined immunodeficiency (SCID) mice and the administration of a monoclonal antibody (mAb) against CCR6 in a rheumatoid arthritis model." (PMID 30453514, 2018). "However, it has been shown that CCL-20 plays a role in the recruitment of immature dendritic cells and precursors to sites of infection and injury and that CCL-20 is involved in pathologies of the endothelial surfaces, such as inflammatory bowel disease and rheumatoid arthritis." (PMID 34831397, 2021). "The in vivo effect of CCL20 inhibition was evaluated using a SKG mouse model, which is primarily a model for rheumatoid arthritis (RA), rather than OA." (PMID 39364408, 2024). "Indeed, increased levels of CCL20, the chemokine attracting CCR6+ cells, were detected in SpA joints, albeit not as prominent as in rheumatoid arthritis." (PMID 29922283, 2018).
asthma (37 papers, 2011 to 2025). "In the airway epithelium, CCL20 is associated with mucus hypersecretion in asthma and promotes Th17-mediated neutrophilic airway inflammation, an asthma endotype that is associated with decreased response to glucocorticoids." (PMID 38057814, 2023). "Many genes, including Il33, Cxcl5, Cxcl15, Ccl20, Cxcl3, Cxcl1, C3, and Pfn1, which have been linked to asthma pathogenesis, showed a cell type-specific response to HDM." (PMID 35627266, 2022). "As for CCL20, the secretion of CCL20 is substantially increased by pathogenic substances in the pathogenesis of asthma." (PMID 35743888, 2022). "Older patients with asthma with elevation of IL-1β, IL-6, and MIP-3a/CCL20 levels were reported to have a greater risk of hospitalization, along with those with IL-6- and IL-23-deteriorated asthma control." (PMID 36291665, 2022). "Asthma and allergies were significantly associated with CCL20 and CCL17, p < 0.03, respectively." (PMID 40181810, 2025). "Collectively, these findings suggest that CCR6+ Treg cells trafficking via CCL20, may be associated with the pathology of asthma." (PMID 34497608, 2021). "Decreased miR-146a-5p expression might be associated with increased CCL20 production from airway smooth muscle cells, which might contribute to enhanced mucus production in asthma." (PMID 30696075, 2019). "What is essential is that MIP-3α/CCL20 primarily attracts Th17 cells and is associated with neutrophilic inflammation and severe asthma phenotypes, suggesting that the efficacy of these three biologics may be partially influenced by the inhibition of Th17-associated inflammatory pathways." (PMID 41155381, 2025). "At the same time, it can also be found that the expression of CCL-20 in alveolar epithelium and the recruitment of DCs are reduced in a mouse model of asthma, thereby inhibiting the allergic state." (PMID 39896814, 2024). "The marker CD196 also called chemokine receptor 6 (CCR6), and its ligand CCL20, contributes to the recruitment of Th17 cells and Th2 cells to the injured tissue and specially deal with the asthma exacerbation." (PMID 32582180, 2020). "Both CCL2 and CCL20 have been proposed as pivotal in the increased steady-state numbers of DCs in the bronchial mucosa of patients with asthma, with a notable increase in Der p 1–dependent CCL20 release in airway samples in atopic asthma." (PMID 29976563, 2018). "In conclusion, S1P/S1PR3 pathway has a role in release of CCL20, which has a role in experimental asthma mouse model, from bronchial ECs." (PMID 30192865, 2018). "IL-36γ has also been shown to induce CCL20, a Th17 cytokine, in lung fibroblasts due to asthma and COPD and in dermatoses via LL-37." (PMID 27379082, 2016). "Differential activation of signaling pathways led to changes in the production of the asthma-relevant cytokines CCL20, CCL2, and IL-10." (PMID 24736642, 2014). "Several studies have demonstrated that IL-17F plays a pivotal role in allergic airway inflammation and induces several asthma-related molecules such as CCL20." (PMID 24829928, 2014). "In the mouse model of asthma, the CCL20/CCR6 system plays a pivotal role in allergic airway responses such as airway resistance, airway eosinophilia, and production of IL-5 and IgE." (PMID 22013453, 2011). "Furthermore, the observed pronounced upregulation of CCL20 expression and secretion may indicate the involvement of Th17-type responses, which are typical in host defence against bacteria and fungi and are relevant in occupational asthma linked to microbial exposure." (PMID 41368042, 2025). "The induction of chemokines CCL20 and IL–8/CXCL8 by GCs was previously reported in human macrophages, enhanced CCL20 expression was reported in GC-insensitive neutrophilic airway inflammation in asthma and elevated CCL20 expression was found in keratinocytes in GC-exacerbated skin conditions." (PMID 39744635, 2024).
asthma (continued). "However, the obese type 2-high asthma group demonstrated a decrease in IL-8 at 6 months that returned to baseline at 12 months, with increased CCL20 at 12 months, and G-CSF decreased at 3 and 6 months but increased at 12 months." (PMID 39200943, 2024). "CCL20 is also higher in individuals with overweight/obese asthma and may explain the corticosteroid resistance observed in these patients." (PMID 38057814, 2023). "The current findings suggest that CCL20 has a crucial role in our experimental asthma model." (PMID 30192865, 2018). "CCL20 is a chemokine derived from bronchial epithelial cells in response to several stimuli such as proinflammatory cytokines and ambient particulate matter, and is involved in the pathogenesis of asthma." (PMID 28628664, 2017). "Furthermore, increased CCL20 levels have been shown in sputum obtained from patients with severe asthma." (PMID 25172034, 2014). "CCL20 has a pivotal role in the pathogenesis of asthma, and is strongly derived from bronchial epithelial cells in response to a broad spectrum of asthma-related stimuli such as pro-inflammatory cytokines, ambient particulate matter, and the proteolytic allergen Der p1." (PMID 22013453, 2011). "CCL20 is involved in the pathogenesis of airway inflammatory diseases including asthma." (PMID 22013453, 2011). "However, further in vivo study is needed to clarify the importance of the IL-17F/CCL20 axis in asthma." (PMID 22013453, 2011). "The IL-17F/CCL20 axis may be a novel pharmacological target for asthma." (PMID 22013453, 2011). "Taken together, the IL-17F/CCL20 axis may have an orchestrating role in the pathogenesis of asthma and could possibly provide a valuable therapeutic target for development of new strategies to treat asthma." (PMID 22013453, 2011). "Specifically, the glucan component of asthma allergen HDM can be recognized by Dectin-1 in epithelial cells, leading to the secretion of C–C motif chemokine ligand 20 (CCL20)." (PMID 38459541, 2024). "At the CCL20 locus, the reQTL (rs13034664) in PHA-stimulated T cells colocalised with childhood-onset asthma." (PMID 32724101, 2020). "S1P induced the expression of some asthma-related genes, such as ADRB2, PTGER4, and CCL20, in the bronchial epithelial cells." (PMID 30192865, 2018). "CCL20 was reported to be secreted from bronchial ECs and regulates the recruitments of DCs which is critical for type 2 helper (TH2) responses in asthma." (PMID 30192865, 2018). "When airway epithelial cells were exposed to plasma from the obese non-asthmatic group, IL-8, CCL20, G-CSF, and IL-6 levels decreased, with a similar trend in the obese type 2-low asthma group." (PMID 39200943, 2024). "No previously reported asthma-related genes except for CCL20 showed more than 4-fold upregulation or down-regulation in both cell lines." (PMID 30192865, 2018). "To evaluate the role of CCL20 on bronchial asthma, we employed OVA-induced asthma mouse model." (PMID 30192865, 2018). "Twenty-four hours after the last OVA challenge, we performed BAL analyses and confirmed that the anti-CCL20 antibody reduced eosinophil percentage of total from 17% to 2% and significantly decreased eosinophil counts in the OVA-induced asthma mouse model (P<0.01)." (PMID 30192865, 2018). "However, a large dataset, focused on a healthy cohort, allowed us to identify statistically significant differences in the expression of CCL20, CCL2 and IL-10, all of which are important during rhinovirus infection and virally induced asthma exacerbations, after exposure with HRV16 and HRV1A." (PMID 24736642, 2014). "However, while the 3 mg protein/ml SHE solution did not induce asthma, co-exposure with DEP resulted in a markedly enhanced AHR (p = 0.002) and eosinophilic inflammation (p = 0.004), with increased levels of IL-5, IL-17F and CCL20 and decreased levels of IFN-γ." (PMID 28628664, 2017).
autoimmune disease (32 papers, 2006 to 2026). A disorder resulting from loss of function or tissue destruction of an organ or multiple organs, arising from humoral or cellular immune responses of the individual to their own tissue constituents. "The recruitment of Th17 cells via the CCL20/CCR6 axis was associated with development of autoimmune diseases, thereby rendering the CCL20/CCR6 axis a prospective novel target for the management of autoimmune conditions, inclusive of CP/CPPS." (PMID 38801403, 2024). "Newly identified PBC risk loci overlap with those of other autoimmune disorders and harbour several immunologically relevant candidate genes, most notably chemokine ligand 20 (CCL20) and interleukin 12B (IL12B)." (PMID 26394269, 2015). "Data from these results indicate that the CCL20/CCR6 axis is implicated in the pathogenesis of autoimmune diseases and that antibodies or antagonists to CCR6 or CCL20 hold promise as an intriguing treatment tactic to ameliorate neuroinflammation and autoimmunity." (PMID 35702353, 2022). "Upregulation of these inflammatory mediators has been linked to the pathogenesis of autoimmune disorders, and plays a potential role in tumor progression and metastasis as well as the pathogenesis of autoimmune neurological diseases (CCL20)." (PMID 34574641, 2021). "Finally, CCR6 and its ligand CCL20 (MCP-3α) coordinate regulation of effective humoral responses also have been linked to autoantibody-driven autoimmune diseases including lupus." (PMID 31921124, 2019). "Given the shared Th17-driven inflammatory pathology between irAEs and autoimmune diseases, targeting CCL20 represents a possible therapeutic strategy for precision management." (PMID 40722787, 2025). "Previous studies have shown that CCL20-CCR6 plays an important role in a variety of autoimmune diseases, such as RA, IBD, and other diseases, and the level of CCL20 is associated with disease severity, as well as in EAU." (PMID 36233291, 2022). "Ccl20 binds to its unique receptor, Ccr6, to recruit Th17 cells and B cell subsets that have important roles in progression of autoimmune disease." (PMID 35472067, 2022). "Homeostasis disruption of CCR6/CCL20 axis plays a critical role in inflammation and autoimmune diseases, suggesting the potential of CCR6 as therapeutic target for patient treatment." (PMID 34225700, 2021). "Although the chemokine CCL20 has been involved in autoimmune diseases, its relationship with the pathogenesis of AAA is unclear." (PMID 29229985, 2017). "Excessive levels of CCL20 may trigger an exaggerated inflammatory response and even contribute to autoimmune disease development." (PMID 39228662, 2024). "In addition, ccl20 is a chemokine whose sole ligand is c-c motif chemokine receptor 6 (ccr6), and it also plays an important role in autoimmune diseases." (PMID 37238005, 2023). "In addition, CCL20 derived from macrophages contributes to the growth and invasion of several tumors and autoimmune diseases." (PMID 35841069, 2022). "Previous studies have demonstrated that CCL20 is markedly upregulated in autoimmune disorders such as inflammatory bowel disease (IBD) and arthritis, and anti-CCL20 antibodies have shown efficacy in ameliorating symptoms in clinical trials." (PMID 40722787, 2025). "The dysregulation of CCL20 or CCR6 can give rise to a large number of diseases including many inflammatory and autoimmune diseases." (PMID 38472446, 2024). "The CCL20/CCR6 axis plays a crucial role in the development of cancers and autoimmune diseases by promoting cell proliferation and migration and remodeling the immune microenvironment." (PMID 35841069, 2022). "CCL20, also known as liver activation regulated chemokine (LARC) or macrophage inflammatory protein-3α (MIP-3α), is a pro-inflammatory chemokine that has been involved, together with its receptor CCR6, in cancer metastasis and various autoimmune diseases." (PMID 36835506, 2023).
autoimmune disease (continued). "When CCL20 binds to its receptor CCR6, it not only participates in regulating the immune homeostasis of the body, but also serves to modulate the inflammatory response through the Th17 pathway, playing an essential role in the progression of autoimmune diseases and various malignant tumors." (PMID 35702353, 2022).
colitis (27 papers, 2013 to 2025). Inflammation of the colon. "We aimed at addressing the function of γδ T cells and their chemoattraction via CCL-20 in our CAC model by injecting anti-γδTCR at day 3 of the 1.5% AOM/DSS protocol prior to the colitis phase of CAC into control and IL-6Rα-deficient animals." (PMID 29695802, 2018). "Importantly, CCL20 is known to recruit pathogenic lymphocytes by acting on its receptor CCR6 in colitis and molecules targeting the CCL20/CCR6 axis are already in clinical development." (PMID 40342995, 2025). "Collectively, these experiments suggest that CCL-20 is expressed by M2-type macrophages in colitis and that the inability of IL-6Rα-deficient macrophages to polarise towards M2-type impedes on CCL-20 expression and presumably on recruitment of CCR-6-expressing cells." (PMID 29695802, 2018). "To directly examine whether the CCL-20/CCR-6 axis is necessary for lymphocyte recruitment during colitis, we investigated CCR-6-deficient mice (Ccr6KO) in our CAC model." (PMID 29695802, 2018). "It has been shown that administration of the GLP‐1 receptor agonist liraglutide to a mouse colitis model induced transcriptional upregulation of the genes Ccl20, Il33 and Muc5b in Brunner's glands, which alleviated colitis." (PMID 41146523, 2025). "In line, experimental colitis in mice was attenuated by treatment with anti-CCL20 neutralizing antibodies, which reduced mucosal T-cell infiltration." (PMID 36232432, 2022). "Treatment of Liraglutide in a T-cell driven adoptive transfer colitis mouse model upregulated expression of IL-33, mucin 5b, and CCL20 in murine Brunner’s glands and improved colitis." (PMID 36386134, 2022). "Suspensions of EPS-producer Lactobacillus paracasei (OD590 = 0.25) inhibited by up to 55% the induction of the CCL20 proinflammatory promoter in Caco-2 cells for flagellin-induced acute colitis model." (PMID 34745425, 2021). "Collectively, these analyses reveal that during colitis CCL-20-recruited CCR-6+ B cells promote CAC." (PMID 29695802, 2018). "Th17 cell activity and migration to the site of colitis is also suppressed by AA through the downregulation of pro-inflammatory Th17 cell recruitment-factor CCL20." (PMID 30037025, 2018). "Moreover, CCL20, TNF-α and COX-2 were likely to play facilitative roles because they had been implicated in the pathogenesis of DSS-induced colitis and human IBDs43,51–55." (PMID 41290870, 2025). "Importantly, we found that growth factors (GFs) like VEGF, IGF, and PDGF as well as chemo-cytokines CCL2, CCL3, CCL4, CCL5, and CCL20 were significantly upregulated in colitis’s colonic tissues." (PMID 37691056, 2023). "PRN694 significantly hindered the development of T-cell-driven adoptive transfer model colitis and T-cell infiltration in tissues, which may be associated with impaired CXCL11 and CCL20 migration." (PMID 36145301, 2022). "Therefore, we conclude that CCL-20 released in the colitis phase recruits CCR-6-expressing lymphocytes that promote CAC tumourigenesis." (PMID 29695802, 2018). "Our results (previous and current) suggest that T-helper 17 cell activity and migration to the site of colitis is suppressed by AA via CCL20 gene downregulation at both time points (3 days post-AA and 28 days post-AA), which makes CCL20 an attractive therapeutic target possibility." (PMID 30037025, 2018). "However, also control IEC samples exhibited increased Ccl20 expression in colitis either via IEC-derived Ccl20 expression or potentially via contaminating macrophages in the samples." (PMID 29695802, 2018). "In a T-cell-driven adoptive transfer (AdTr) colitis mouse model, liraglutide significantly improved disease activity markers, including histological activity in colonic tissue and the colon weight-to-length ratio, likely due to its ability to reduce CCL20, IL-33, and IL-22." (PMID 40426955, 2025).